C20orf173 (chromosome 20 open reading frame 173)
Synonyms: dJ477O4.4
Tractability: Antibody: the Human Protein Atlas places it where antibodies can reach.
Gene: Protein-coding gene on chromosome 20 (35,523,186 to 35,529,652, reverse strand). Ensembl gene ENSG00000125975.
Subcellular location (Human Protein Atlas): Nucleoplasm; Plasma membrane; Vesicles
Gene Ontology:
Molecular function: protein binding; beta-galactoside (CMP) alpha-2,3-sialyltransferase activity; sialyltransferase activity
Biological process: glycoprotein biosynthetic process; sialylation
Cellular component: membrane
Genetic constraint (gnomAD): Loss-of-function variants: 22 observed, 27.38 expected, observed/expected ratio (o/e) 0.8, 90% interval 0.57 to 1.15. The upper end of that interval is the gene's LOEUF score, 1.15, which puts it in group 5 of 6, group 1 being the genes least tolerant of losing a copy. Missense variants: 210 observed, 256.96 expected, observed/expected ratio (o/e) 0.82, 90% interval 0.73 to 0.92. Synonymous variants: 85 observed, 101.19 expected, observed/expected ratio (o/e) 0.84, 90% interval 0.7 to 1.01.
Homologues: Orthologues: chimpanzee C20H20orf173 (97% identical), macaque C20orf173 (87% identical), dog C24H20orf173 (56% identical), mouse 6430550D23Rik (40% identical), rat C3h20orf173 (39% identical), zebrafish st3gal8 (19% identical), zebrafish st3gal7 (16% identical). Paralogues in human: ST3GAL1 (21% identical), ST3GAL2 (17% identical), ST6GALNAC1 (17% identical), ST6GAL2 (15% identical), ST3GAL4 (14% identical), ST3GAL5 (14% identical), ST6GALNAC5 (13% identical), ST3GAL3 (12% identical), ST6GALNAC4 (12% identical), ST3GAL6 (12% identical), ST6GALNAC2 (12% identical), ST6GAL1 (10% identical), and 2 more.
Diseases named in the same sentence as C20orf173 in open-access papers:
C20orf173 is named in the same sentence as 2 diseases in open-access papers, as found by Europe PMC text mining. Sharing a sentence is not in itself a finding about the gene and the disease. The quoted sentences say what the papers report.
emphysema (1 paper, 2025). "Notably, protein FAM177A1, syntenin-2, and uncharacterized protein C20orf173 explained an additional 0.54%, 0.41%, and 0.38% of the variance in percent emphysema, respectively." (PMID 40616090, 2025).
C20orf173 also shares sentences with these, for which no sentence is quoted: male infertility (1 paper).